ISG15 (ISG15 ubiquitin like modifier)
Diseases named in the same sentence as ISG15 in open-access papers (continued):
Sharing a sentence is not in itself a finding about the gene and the disease.
tumor (continued). "Our experiments revealed that Isg15+ neutrophils recruited to tumor sites suppressed cancer initiation and metastasis, indicating that not all tumor-associated neutrophils promote cancer growth and reflecting the plasticity of neutrophil function." (PMID 39979981, 2025). "ISG15 also coordinates immune–metabolic interactions in the tumor microenvironment." (PMID 41193953, 2025). "In recent years, increasing number of studies have shown that ISG15 has a complex regulatory role in the tumor microenvironment (TME) and tumor progression, and may have different effects in different cancers." (PMID 41193953, 2025). "Finally, experiments in oral squamous cell carcinoma (OSCC) revealed that extracellular ISG15 produced from OSCC cells promote changes in tumor microenvironment by inducing fibroblasts recruitment, potentially having an effect in cancer progression." (PMID 40719862, 2025). "As for genes enrolled in IFN‐γ response, ISG15 was highly expressed in tumours with ICI treatment." (PMID 39934971, 2025). "However, a clear conclusion on the relationship between ISG15 and tumor immune infiltration has yet to be seen." (PMID 40208307, 2025). "ISG15 has demonstrated tumor-suppressing and tumor-promoting effects in different tumor types." (PMID 40936712, 2025). "Moreover, ISG15 facilitates the induction of E-cadherin on tumor-infiltrating dendritic cells (DCs), aiding tumor immune evasion." (PMID 40103488, 2025). "ISG15+CD163+ macrophages inhibit the anti-tumor activity of CD8+ T cells in NPC." (PMID 40103488, 2025). "The findings of this study may provide comprehensive information about ISG15 in predicting tumor patient prognosis and the responses to immunotherapy." (PMID 40208307, 2025). "Notably, we identified PRDM6, a histone methyl-transferase previously unlinked to HNSCC, as a key regulator of immune gene expression in HNSCC tumor cells, including canonical interferon-stimulated genes (ISGs) such as ISG15 and IFITM1." (PMID 40936897, 2025). "For example, assessing ISG15 expression levels in tumor biopsies may help identify patients more likely to benefit from immune checkpoint inhibitors or combination therapies, paving the way for more personalized treatment strategies." (PMID 40208307, 2025). "Interestingly, ISG15 also exhibits anti-tumour effects under specific conditions, largely through extracellular functions and immune regulation." (PMID 40103488, 2025). "Furthermore, free ISG15 has been shown to inhibit tumor growth when administered extracellularly, inducing the infiltration of NK cells into tumors in nude mice." (PMID 40158006, 2025). "Depending on the cancer type, cellular context, and immune status, ISG15 may act either as a tumor suppressor or as a promoter of malignancy." (PMID 41193953, 2025). "We also performed mIHC to confirm the expression of ISG15 in the tumour and normal bowel wall." (PMID 39934971, 2025). "ISG15 has a significant tumor type-specific pattern of immune regulation." (PMID 41193953, 2025). "Thus, free or conjugated forms of ISG15 have a complex role in tumorigenesis in a wide range of human tumours and cancer cell lines." (PMID 38939897, 2024). "Interferon-stimulated gene 15 (ISG15) is known to influence tumor growth and severity." (PMID 38443596, 2024). "Taken together, our data suggests that necroptosis-specific ISG15-RAGE axis may contributes to HNSCC progression through promoting tumor-cell dissemination, thus leading to poor prognosis." (PMID 38926796, 2024). "Furthermore, CD45neg tumor/stromal cells in B16 tumors treated with ADU-S100 + anti-ISG15 (vs. ADU-S100 alone) expressed higher levels of MHC II, with a trend for increased expression of PD-L1 (p = 0.1042)." (PMID 38312842, 2024).
tumor (continued). "Finally, Cluster 8 was equally conserved across healthy and tumor-associated neutrophils and was enriched for IFN markers: Isg15, Rsad2, Ifit3, Ifit1, and Slfn4, a phenomenon previously reported in several scRNA-seq studies of neutrophils." (PMID 38358352, 2024). "Additionally, our animal experiments confirmed that sustained ISG15 knockdown reduced tumor growth rate in nude mice and promoted cell apoptosis." (PMID 38951255, 2024). "The intracellular monomeric ISG15 plays a dual regulatory role in tumour cells." (PMID 38400136, 2024). "Our observation that (ADU-S100 induced) ISG15 mediates pro-tumor effects in the TME that may be antagonized for therapeutic gain is novel." (PMID 38312842, 2024). "Many downregulated genes in tumour‐infiltrating peripheral CD8+ T cells are associated with classical IFN responses (IFI6, IFI27, MX1, STAT1, EPSTI1 PARP9, ISG15), cell proliferation (STMN1, CENPF, HELLS, NUSAP1, and DNPH1), and T cell costimulation (CD28, TMIGD2, TNFRSF4, CD27, and TNFRSF18)." (PMID 39350478, 2024). "ISG15 serves important roles in immune regulation and tumor development." (PMID 39272848, 2024). "The other group comprises macrophage subgroups, including Mφ-STMN1, Mφ-ISG15, tissue-resident macrophages (RTM-LMNA, RTM-MARCO), tumor-associated macrophages (TAM-MMP12, TAM-SPP1, TAM-CXCL10, TAM-HLA-DQA1), and myeloid-derived suppressor cell-like cells (MDSClike-IL10)." (PMID 39308672, 2024). "Animals treated with ADU-S100 + anti-ISG15 had a significant increase in the frequency of tumor infiltrating CD62L+CD44+ central memory CD8+ and CD4+ T cells compared to those treated with ADU-S100 alone, as well as an increase in CD44+CD62L- effector CD4+ TIL." (PMID 38312842, 2024). "These complex biological responses might result from the pleiotropic actions of ISG15 and ISGylation as well as various feedback control mechanisms, which appear to be dependent on the tumor context and tumor microenvironment." (PMID 38443596, 2024). "Also, the significantly reduced tumor weight in the ISG15-sh2+Gemci group when compared with the ISG15-NC+Gemci group indicated that IGS15 confers resistance to Gemcitabine in PC cells." (PMID 38385083, 2024). "Forced expression models suggest that free extracellular ISG15 may initially limit tumor progression in an NK cell-dependent manner, with ISG15 also reported to serve as an effective vaccine adjuvant for CD8+ T cell crosspriming." (PMID 38312842, 2024). "Several layers of difficulty are likely to impinge on any therapy targeting ISG15, given its multiple substrates and cellular functions (including pathogen defense and tumor suppression), its context-specific effects, and the complexity of the pro-inflammatory pathways in which it participates." (PMID 37025175, 2023). "Based on these findings, we speculate that ISG15 mobilize activated splenic T lymphocytes to increase the number of infiltrations in the tumor, so that these T cells have anti-tumor effects into the tumor microenvironment." (PMID 37217923, 2023). "Targeting ISG15 to treat tumours appears to be a promising strategy." (PMID 37217923, 2023). "Such an increase in ISG15 has been previously reported in other tumor CSCs." (PMID 37501099, 2023). "We also harvested a small fraction of co-cultured tumor cells for Western blot and found that ISG15-overexpressed cells showed higher expression of active caspase-3 and Bax proteins and lower expression of Bcl-2 than ISG15-depleted cells." (PMID 37217923, 2023). "We further assessed ISG-15+CD8+ T cells in other EBV-associated tumours and confirmed the existence of ISG-15+CD8+ T cells in EBV (+) ICC but not in EBV (−) ICC tumours via mIHC." (PMID 37735150, 2023). "As IFN-γ produced by activated T cells can upregulate PD-L1 on the surface of tumour cells, we were interested in whether ISG15 could influence induced PD-L1 expression." (PMID 37217923, 2023).
tumor (continued). "Importantly, upregulation of Type I interferon responsive genes, especially ISG15, was observed in major tumor infiltrating APCs, particularly DCs and macrophages." (PMID 36911698, 2023). "Also, ISG15 has been reported to promote tumor cell migration and was considered to induce the immunosuppressive phenotype of macrophages." (PMID 37483625, 2023). "Moreover, the expression of VEGFA was significantly higher in the TN, whereas the IFN‐stimulated gene (e.g., ISG15) was higher in the tumour edge." (PMID 37491740, 2023). "Furthermore, we identified several tumour-associated macrophages, including C1QC+ macrophages, ISG-15+ macrophages, NLRP3+ macrophages and CCL20+ macrophages." (PMID 37735150, 2023). "ISG15 and PD-L1 form ISGylation which involving k-48 ubiquitin-chain and then destabilizes glycosylated PD-L1 and promotes its degradation through the ubiquitin–proteasome pathway, thus activating anti-tumor immune function." (PMID 37217923, 2023). "The regulation of intracellular monomeric ISG15 on tumor cells has also been reported." (PMID 36771004, 2023). "Firstly, ISG-15+CD8+ T cell subsets could be universally found in EBV (+) tumours, such as GC, NPC and ICC." (PMID 37735150, 2023). "In addition, reduced accumulation of PD-L1 by ISG15 in mice also increased splenic lymphocyte infiltration as well as promoted cytotoxic T cell infiltration in the tumor microenvironment, thereby enhancing anti-tumor immunity." (PMID 37217923, 2023). "Several studies have confirmed the dysregulation of ISG15 and ISGylation expression in tumours." (PMID 37217923, 2023). "These exploratory findings require more detailed study of the LMP1/IRF7 pathway, if anti-viral or anti-cancer immunity is mediated by ISG15, and to determine whether type I IFNs are exerting a pro- or anti-tumor effect in BL tumors." (PMID 36878637, 2023). "For instance, the MeC derived from the largest IC cluster is highly enriched in interferon response genes, such as ISG15, IFI6, LY6E, and MX1, indicating that the underlying interferon response is among the most common source of transcriptional variation shared across tumor samples and cohorts." (PMID 37149682, 2023). "We performed single cell RNA sequencing (scRNAseq) on tumor-infiltrating lymphocytes, which demonstrated activation of Type I interferon pathway, particularly upregulation of ISG15 in DCs, macrophages and monocytes of tumor-bearing mice receiving TA99-HL2-KOA1 treatment." (PMID 36911698, 2023). "Interestingly, we found the apoptosis of tumor cells in the Lv-ISG15 group was more obvious after co-culture than in the Sh-ISG15 group." (PMID 37217923, 2023). "An important question regarding the decreased ISG-15+CD8+ T cell abundance in a responsive on-treatment tumour is whether they are transitory cells." (PMID 37735150, 2023). "In summary, further studies are warranted to determine the role of ISG15/ISGylation in different cancer types, since its effect might be tumor suppressive or oncogenic depending on the context." (PMID 37025175, 2023). "Our data support that autocrine tumour-secreted ISG15 may also play a role in CSC enhancement in an SFT context." (PMID 35864381, 2022). "ISG15 is a stress response gene that may act as a contributor to tumor suppressors and inflammatory responses." (PMID 35739944, 2022). "Furthermore, ISG15 expression was successfully used to distinguish between non-metastatic and lymph node metastatic TC, while in mice, knock down of ISG15 inhibited xenografted tumor growth." (PMID 35406748, 2022). "Recent studies have focused on the role of ISG15 in other major cellular processes, such as DNA repair, autophagy or protein translation, as well as in pathological contexts like genotoxic stress or tumour development." (PMID 35864381, 2022). "Here, we describe the role of ISG15 in the biology of this rare tumour." (PMID 35864381, 2022).
tumor (continued). "Moreover, ISG15 promoted malignant phenotypes of esophageal squamous cells, including proliferation, migration, invasion, and tumor formation in vivo." (PMID 35159348, 2022). "Multivariate analysis demonstrated that high protein expression of ISG15 was associated with shorter BCSS [p = 0.026, Hazard ratio, 1.3, 95% CI 1.0–1.6], independent of other established prognostic factors including LVI, tumour size, histological grade, ER and HER2 status." (PMID 33073304, 2021). "Furthermore, free form ISG15 can also be released extracellularly and alters the tumour microenvironment via functioning as an immunomodulatory cytokine." (PMID 33797839, 2021). "Epithelial-immune tumor cells expressed high levels of immune-related genes that included interferon (IFN)-response genes [e.g. IFN-stimulated gene 5 (ISG15)], major histocompatibility complex II (MHC II)-coding genes (e.g. HLA-DR), and complement genes (e.g. C3)." (PMID 33718235, 2021). "These contradictory findings suggest that ISG15 expression in the tumor could be a factor affecting chemotherapy treatment of cancer and the contribution of ISG15 in tumor chemosensitivity may be tissue specific." (PMID 33718235, 2021). "This could explain the reflection of poor prognosis and tumour development when ISG15 is highly expressed." (PMID 33073304, 2021). "Therefore, deregulation in the expression of ISG15 may be expected to have pro-tumor functions, and thus an increased ISG15 level may promote carcinogenesis, giving the possibility of its use as a high-confidence diagnostic, therapeutic, and immunostimulant tumor biomarker." (PMID 34439992, 2021). "However, ISG15 plays a role not only in promoting tumor progression but also in preventing tumor development." (PMID 34696780, 2021). "As a consequence of immune cell infiltration into the tumour stroma and because these cells are the main source of interferon α and β, this may lead to increased ISG15 expression in tumour cells." (PMID 33073304, 2021). "Based on these results they concluded that ISG15 acts as a stimulator of tumor growth and therefore might have a therapeutic potential." (PMID 34781949, 2021). "ISG15 has both immunomodulatory pro-tumor and anti-tumor functions." (PMID 33718235, 2021). "Survival data analysis revealed that negative ISG15 expression was associated with significantly shortened survival time (P = .0036) after removal of the primary tumour." (PMID 33797839, 2021). "Currently, there are still many controversies regarding whether ISG15 exerts a tumor-suppressing effect or a cancer-promoting effect." (PMID 34901029, 2021). "Moreover, the extracellular ISG15 acts as an immune adjuvant that promotes antigen-specific CD8 + T cell tumour immunity." (PMID 33073304, 2021). "However, in basal tumours with lymph node metastasis a positive correlation between ISG15 mRNA and pAkt was found (P value = 0.0012)." (PMID 34556814, 2021). "Moreover, studies have shown that unconjugated ISG15 exerts a cancer-promoting function by enhancing the stem transformation and proliferation of tumor cells." (PMID 34901029, 2021). "The role of secreted ISG15 during tumour development is contradictory." (PMID 34556814, 2021). "Additionally, the attenuation of tumor growth when knocking down ISG15 with shRNA implied that ISG15 probably serves as a prognosis indicator in fluid biopsy of thyroid papillary microcarcinoma patients with LNM." (PMID 32411222, 2020). "Interferon-stimulated gene 15 (ISG15) is known to be involved in tumor progression." (PMID 33424843, 2020). "Conversely, ISG15 depletion, K-to-R mutations of ΔNp63α ISGylation sites, or D-to-A mutations of CASP2 cleavage sites markedly potentiate ΔNp63α-mediated anchorage-independent cell growth and tumour development in vivo." (PMID 33203188, 2020). "Since cytotoxic CD8+ T cell has cytotoxic activity against tumor cells, we determined whether ISG15+ TAMs may impair the intrinsic functionality of CTLs." (PMID 33424843, 2020).
tumor (continued). "In small cell and non-small cell type lung cancer patients, more than 70% of patients have a deletion in the chromosome 3p21 region, and UBE1L is located in this region, so it is suggested that ISG15 may be a tumour suppressor gene for lung cancer." (PMID 32641707, 2020). "Therefore, the effect of free ISG15 on immune cells in the tumour microenvironment will also be the focus of our further research." (PMID 32641707, 2020). "Out of 90 NPC cases, 87 specimens (96.6%) expressed CD163+ cells, 57 specimens (63.3%) stained ISG15 mainly in tumor cells and infiltrating immune cells, and 49 specimens (54.4%) expressed ISG15+ CD163+ cells, which suspected to be macrophages based on their morphology as well." (PMID 33424843, 2020). "Other study identified in BC tumours elevated ISG15 expression when compared with normal tissue." (PMID 30792808, 2019). "ISG15 is suggested to operate much like ubiquitin and brings about the conjugation (ISGylation) of ISG15 to a wide variety of proteins (between 100–300 proteins) and both pro-tumorigenic and tumor suppressive roles have been suggested for increased ISG15 expression in various types of cancer." (PMID 31903170, 2019). "Finally, we detected increased ISG15 expression in human CRC tissue in tumor cells and in the adjacent stroma, while the normal mucosa did not display detectable ISG15 staining." (PMID 31903170, 2019). "It has been shown that ISG15 can promote cancer stem cell growth, yet it still remains an open question whether it is a pro- or anti-tumor factor." (PMID 30987352, 2019). "Additionally, extracellular ISG15 acts as an immune adjuvant to enhance antigen-specific CD8+ T cell tumor immunity." (PMID 30469497, 2018). "We showed here by Western blot analysis that up-regulated endogenous ISG15 in cancer cells increased the amount of ISGylated ERK1 and decreased the expression levels of phospho-ERK1 and ERK down-stream genes that are associated with tumor progression." (PMID 30469497, 2018). "We therefore hypothesized that high levels of free ISG15 secreted by tumor cells play a role in CD8+ T cell activation." (PMID 30469497, 2018). "Thus, the expression of HERC5 and other parts of the ISG15 protein degradation system seems to be tumor type specific." (PMID 29027969, 2017). "Opposing methylation states among tumor subtypes relative to normal tissue may contribute to subtype-specific roles of ISG15 dysregulation in breast carcinogenesis." (PMID 28912426, 2017). "This study highlighted a novel role of ISG15 in tumor suppression." (PMID 27659523, 2016). "With regard to cancers of the digestive system, the bulk of the most compelling current evidence suggests that ISG15 can function as a tumor suppressor, based on correlations of enhanced ISG15 expression and ISGylation with responses to various chemotherapeutic drugs." (PMID 27626310, 2016). "In addition to the intracellular system, free ISG15 is also secreted into the extracellular milieu and acts as an immunomodulatory cytokine in the tumor microenvironment." (PMID 26919245, 2016). "We demonstrated that ISG15 mRNA was significantly up-regulated in tumor tissues." (PMID 26919245, 2016). "Whether ISG15 functions as a tumor suppressor or promotes tumorigenesis remains largely unclear, due at least in part to the multitude of cellular process in which ISG15-conjugates are involved." (PMID 27626310, 2016).